CCDC34 (coiled-coil domain containing 34)
Description:
Involved in spermatogenesis. Has a probable role in anterograde intraflagellar transport which is essential for the formation of sperm flagella.
Synonyms: RAMA3; L15; NY-REN-41; SPGF76
Tractability: PROTAC: ubiquitination databases record sites on it.
Gene: Protein-coding gene on chromosome 11 (27,330,827 to 27,363,248, reverse strand). Ensembl gene ENSG00000109881.
Subcellular location: Cell projection, cilium, flagellum
Subcellular location (Human Protein Atlas): Calyx; Mid piece; Nuclear membrane; Nucleoli fibrillar center; Connecting piece; End piece; Principal piece
Gene Ontology:
Biological process: spermatogenesis
Cellular component: sperm end piece; sperm head-tail coupling apparatus; sperm midpiece; sperm principal piece; motile cilium
Genetic constraint (gnomAD): Loss-of-function variants: 26 observed, 33.4 expected, observed/expected ratio (o/e) 0.78, 90% interval 0.57 to 1.08. The upper end of that interval is the gene's LOEUF score, 1.08, which puts it in group 4 of 6, group 1 being the genes least tolerant of losing a copy. Missense variants: 406 observed, 396.23 expected, observed/expected ratio (o/e) 1.02, 90% interval 0.94 to 1.11. Synonymous variants: 138 observed, 146.54 expected, observed/expected ratio (o/e) 0.94, 90% interval 0.82 to 1.09.
Homologues: Orthologues: chimpanzee CCDC34 (98% identical), macaque CCDC34 (94% identical), pig CCDC34 (82% identical), rabbit CCDC34 (82% identical), rat Ccdc34 (71% identical), mouse Ccdc34 (69% identical), guinea pig CCDC34 (58% identical), tropical clawed frog ccdc34 (39% identical), zebrafish ccdc34 (29% identical), Drosophila melanogaster CG14011 (18% identical), Drosophila melanogaster CG18266 (17% identical), Drosophila melanogaster CG7251 (12% identical).
Diseases named in the same sentence as CCDC34 in open-access papers:
CCDC34 is named in the same sentence as 10 diseases in open-access papers, as found by Europe PMC text mining. Sharing a sentence is not in itself a finding about the gene and the disease. The quoted sentences say what the papers report.
bladder cancer (4 papers, 2015 to 2024). "The enhancer where rs2472632 is located is predicted to target the CCDC34 gene, an oncogene that has been reported to be up-regulated in bladder cancer, cervical cancer, colorectal cancer, and PDAC." (PMID 38308339, 2024). "The results showed that CCDC34 expressed higher level in bladder cancer specimens than in the paraneoplastic normal bladder tissues (P = 0.012)." (PMID 26312564, 2015). "In our study, Lentivirus-mediated CCDC34 knockdown markedly inhibited bladder cancer cell proliferation and migration in vitro." (PMID 26312564, 2015). "The detailed mechanisms of CCDC34 in regulating bladder cancer tumorigenesis and progression would also need further studies." (PMID 26312564, 2015). "To confirm the results, we performed Western blot to detect CCDC34 expression in 18 bladder cancer specimens which were diagnosed by histopathological examination." (PMID 26312564, 2015). "We used lentivirus-mediated specific siRNA targeting of CCDC34 to investigate the role of its silencing on the proliferation, migration and cell cycle progression of bladder cancer cells." (PMID 26312564, 2015). "The knockdown of CCDC34 via lentivirus-mediated siRNA significantly suppressed bladder cancer cells proliferation and migration, and induced cell cycle arrest at G2/M phase and increased apoptosis in vitro." (PMID 26312564, 2015). "To investigate the mechanism by which CCDC34 contributes to malignancy of bladder cancer, we did Lentivirus-mediated knockdown of CCDC34 in T24 and 5637 cells." (PMID 26312564, 2015). "Next, we performed Western blot to detect CCDC34 expression in the bladder cancer cell lines 5637, T24, J82, EJ and BIU-87, and the normal human urinary tract epithelial cell line SV-HUC-1." (PMID 26312564, 2015). "During our study, we did a preliminarily functional characterization of CCDC34 expression in bladder carcinomas." (PMID 26312564, 2015). "Moreover, evidence revealed that ERK1/2 and p38 play a role in CCDC34-mediated bladder cancer cell proliferation and migration." (PMID 28060741, 2017). "Next, we would expand the number of our bladder cancer specimens to find whether CCDC34 level is correlated with the tumor grade, pathologic stage and lymph node metastasis to further explore its clinical significance." (PMID 26312564, 2015). "Together, our work provided novel information on the function of CCDC34 in bladder cancer cells." (PMID 26312564, 2015). "Initially, immunohistochemical analysis revealed high expression of CCDC34 in bladder tumors compared with normal urothelium, and Western blot confirmed that CCDC34 was expressed at higher level in human bladder cancer tissues compared with their paraneoplastic bladder tissues." (PMID 26312564, 2015). "So our findings preliminarily declared that CCDC34 silencing may suppress bladder cancer proliferation and migration through inactivation of RAF-ERK1/2-MAPK, p38/MAPK, JNK/MAPK and PI3K/Akt signaling pathways." (PMID 26312564, 2015). "Furthermore, we assayed the colony formation to determine CCDC34 knockdown in bladder cancer cell tumorigenesis in vitro." (PMID 26312564, 2015). "Of the bladder cancer cell lines, T24, 5637 and EJ showed the highest CCDC34 expression." (PMID 26312564, 2015). "Our findings revealed for the first time a potential oncogenic role for CCDC34 in bladder carcinoma pathogenesis and it may serve as a biomarker or even a therapeutic target for bladder cancer." (PMID 26312564, 2015). "Further analysis revealed that significant inactivation of the MAPK and AKT pathways might be involved in CCDC34 regulation of bladder cancer cell proliferation and migration." (PMID 26312564, 2015). "In this study, we examined the expression of CCDC34 in human bladder cancer tissues and cell lines." (PMID 26312564, 2015). "Elevated CCDC34 was detected in human bladder cancer specimens." (PMID 26312564, 2015).
bladder cancer (continued). "Our findings revealed for the first time a potential oncogenic role for CCDC34 in bladder cancer and it might be a useful target for bladder cancer therapy." (PMID 26312564, 2015). "Here, we found CCDC34 expression was elevated in bladder cancer tissues and cell lines." (PMID 26312564, 2015). "However, the biological and clinical significances of CCDC34 in human bladder carcinoma remain largely unknown, prompting us to examine CCDC34 functional roles in bladder carcinoma pathogenesis." (PMID 26312564, 2015). "Moreover, CCDC34 silencing decreased the phosphorylation of MEK, ERK1/2, JNK, p38 and Akt, and the expressions of c-Raf and c-Jun, indicating MAPK and AKT pathways (ERK/MAPK, p38/MAPK, JNK/MAPK and PI3K/Akt) might be involved in CCDC34 regulation of bladder cancer cell proliferation and migration." (PMID 26312564, 2015). "In addition, bladder cancer cell lines 5637, T24 and EJ showed elevated expression of CCDC34, while J82 and BIU-87 did not demonstrate increased CCDC34 expression levels compared with benign cell line SV-HUC-1." (PMID 26312564, 2015). "But two out of five bladder cancer cell lines did not demonstrate increased CCDC34 expression, and this discrepancy might indicate certain relevance of sensitivity of CCDC34 with individual differences in tumor itself and its malignancy." (PMID 26312564, 2015).
bladder tumors (1 paper, 2015). "In addition, CCDC34 knockdown suppressed bladder tumor growth in nude mice." (PMID 26312564, 2015).
bladder urothelial carcinoma (1 paper, 2015). "We examined CCDC34 expression in 42 pairs of bladder urothelial carcinoma and matched adjacent normal tissues by immunohistochemical staining." (PMID 26312564, 2015).
pancreatic adenocarcinoma (1 paper, 2024). "In Pancreatic Adenocarcinoma (PAAD) tumor tissues, the CCDC34 gene was significantly overexpressed with p = 1.22 × 10−19 compared to normal pancreas tissues according to the TNMplot database, which has RNA-seq data of tumor and healthy tissues from TCGA and GTEx repositories." (PMID 38308339, 2024).
tumor (4 papers, 2015 to 2025). "CCDC34 siRNA treatment significantly decreased tumor growth, as shown by strongly reduced tumor size and weight compared with the control treatment (3B b, 3B c)." (PMID 26312564, 2015). "The T24 xenograft tumor taken rate in nude mice is 100%, and then the nude mice were randomly selected and treated with CCDC34 siRNA (siCCDC34) or control siRNA (siCtrl) twice a week for 4 weeks by intratumor injection." (PMID 26312564, 2015). "Next, we investigated the effect of therapeutic CCDC34 siRNA on tumor growth in vivo." (PMID 26312564, 2015). "Analysis of the GSE39582 dataset revealed notably elevated expression of CCDC34, FBL, and RAB15 in tumor tissues, whereas AQP11 and HADH were notably downregulated." (PMID 41583431, 2025). "Another validated focal CNA detected in one tumor (WT201) was the 825 kb homozygous deletion at 11p14.1p14.2 (#chr11:26,688,179-27,513,817; GRCh37), harbouring BBOX, among others genes (SLC5A12, FIBIN, CCDC34, LGR4)." (PMID 26913079, 2016).
cancer (3 papers, 2015 to 2020). A tumor composed of atypical neoplastic, often pleomorphic cells that invade other tissues. "Current research have shown that CCDC34 is upregulated in a variety of tumors and contributes to the malignant behaviors of cancer cells." (PMID 33188157, 2020). "The results showed weak staining in normal bladder tissues, while strong staining of CCDC34 was detected in almost all the cancer specimens." (PMID 26312564, 2015). "However, more mechanisms for CCDC34 function in normal bladder and cancer tissues need further exploration." (PMID 26312564, 2015).
adenocarcinoma (1 paper, 2020). A common cancer characterized by the presence of malignant glandular cells. "We also found that SOX4, ORC6, and CCDC34 were more highly expressed in adenocarcinoma tissue than in normal gastric tissue using Western blot (WB) assays and immunohistochemistry (IHC)." (PMID 33188157, 2020). "Moreover, SOX4, ORC6, and CCDC34 are located mainly in the nucleus of adenocarcinoma tissues." (PMID 33188157, 2020).
CCDC34 also shares sentences with these, for which no sentence is quoted: cervical cancer (1 paper); colorectal cancer (1); lymph node metastasis (1).